CTSH (cathepsin H)
Description:
Important for the overall degradation of proteins in lysosomes.
Synonyms: CPSB; ACC-4; ACC-5; ACC4; ACC5
Tractability: Small molecule: a high-quality ligand is known; it belongs to a druggable protein family. Antibody: its Gene Ontology location is reachable by antibodies, with high confidence; UniProt predicts a signal peptide or a membrane-spanning region. PROTAC: ubiquitination databases record sites on it; its protein half-life has been measured; a small molecule that binds it is known.
Target class: Cysteine protease; Cysteine protease CA clan; Enzyme; Protease; Cysteine protease C1A family
Gene: Protein-coding gene on chromosome 15 (78,921,058 to 78,949,574, reverse strand). Ensembl gene ENSG00000103811.
Subcellular location: Lysosome
Subcellular location (Human Protein Atlas): Cytoplasmic bodies; Cytosol; Vesicles
Pathways (Reactome):
Immune System: MHC class II antigen presentation; Neutrophil degranulation
Metabolism of proteins: Surfactant metabolism
Gene Ontology:
Molecular function: aminopeptidase activity; cysteine-type endopeptidase activator activity involved in apoptotic process; cysteine-type endopeptidase activity; cysteine-type peptidase activity; endopeptidase activity; HLA-A specific activating MHC class I receptor activity; peptidase activity; protein binding; thyroid hormone binding; serine-type endopeptidase activity; identical protein binding; kininogen binding; peptidase activator activity involved in apoptotic process; protein-containing complex binding
Biological process: adaptive immune response; bradykinin catabolic process; cellular response to thyroid hormone stimulus; ERK1 and ERK2 cascade; immune response-regulating signaling pathway; lysosomal protein catabolic process; membrane protein proteolysis; neuropeptide catabolic process; positive regulation of cell migration; positive regulation of gene expression; protein destabilization; proteolysis; surfactant homeostasis; zymogen activation; antigen processing and presentation; dichotomous subdivision of terminal units involved in lung branching; immune response; metanephros development; positive regulation of apoptotic signaling pathway; positive regulation of epithelial cell migration; response to retinoic acid; T cell mediated cytotoxicity; apoptotic process; response to odorant; spermatogenesis
Cellular component: alveolar lamellar body; cytosol; extracellular exosome; extracellular matrix; extracellular region; lysosome; ficolin-1-rich granule lumen; multivesicular body lumen; secretory granule lumen; tertiary granule lumen; acrosomal vesicle; axoneme; outer dense fiber
Genetic constraint (gnomAD): Loss-of-function variants: 43 observed, 43.77 expected, observed/expected ratio (o/e) 0.98, 90% interval 0.77 to 1.27. The upper end of that interval is the gene's LOEUF score, 1.27, which puts it in group 5 of 6, group 1 being the genes least tolerant of losing a copy. Missense variants: 391 observed, 397.07 expected, observed/expected ratio (o/e) 0.98, 90% interval 0.91 to 1.07. Synonymous variants: 169 observed, 146.83 expected, observed/expected ratio (o/e) 1.15, 90% interval 1.01 to 1.31.
Homologues: Orthologues: chimpanzee CTSH (99% identical), macaque CTSH (97% identical), pig CTSH (88% identical), dog CTSH (85% identical), guinea pig CTSH (83% identical), mouse Ctsh (83% identical), rat Ctsh (83% identical), zebrafish ctsh (63% identical), Caenorhabditis elegans F15D4.4 (29% identical). Paralogues in human: CTSK (41% identical), CTSV (39% identical), CTSL (38% identical), CTSS (35% identical), CTSF (32% identical), CTSC (29% identical), CTSW (28% identical), CTSO (27% identical), CTSB (24% identical), CTSZ (24% identical), TINAGL1 (22% identical), TINAG (21% identical).
Diseases named in the same sentence as CTSH in open-access papers:
CTSH is named in the same sentence as 87 diseases in open-access papers, as found by Europe PMC text mining. Sharing a sentence is not in itself a finding about the gene and the disease. The quoted sentences say what the papers report.
type 1 diabetes (13 papers, 2015 to 2025). "Emerging translational evidence implicates Cathepsin H in metabolic disorders, with elevated circulating levels associated with type 1 diabetes mellitus (T1DM) risk." (PMID 40616157, 2025). "The lysosomal protease, CTSH, also provides a direct link between lysosome function and type 1 diabetes susceptibility, where the CTSH susceptibility allele is associated with impaired human beta cell function." (PMID 33515072, 2021). "Another type 1 diabetes susceptibility gene, Cathepsin H (CTSH), is a lysosomal cysteine protease that is crucial for lysosomal protein degradation." (PMID 33515072, 2021). "Notably, CTSH has garnered attention for its involvement in type 1 diabetes and narcolepsy risk, both of which prominently feature autoimmune components." (PMID 38521921, 2024). "Finally, we found that the effects of some of these variants colocalized between NT1 and type 1 diabetes (CTSH G11R and SIRPG S286L, posterior probability = 1.0)." (PMID 37188663, 2023). "Cathepsin H (CTSH) is a type 1 diabetes (T1D) risk gene; large-scale genetic and epidemiological studies found that T1D genetic risk correlates with high CTSH expression, rapid decline of beta-cell function, and early onset T1D." (PMID 33992646, 2021). "Type 1 diabetes susceptibility genes have previously been found to interact with Caesarean section (IFIH1) or to be associated with increased progression to stage 3 type 1 diabetes (TNFAIP3, CTSH, MIR2681HG)." (PMID 38819466, 2024). "Additionally, CTSH is an important regulator of β-cell function in type 1 diabetes, where its overexpression protects against β-cell apoptosis, while downregulation promotes cell death." (PMID 40977731, 2025). "Notably, overexpression of CTSH and CTSZ have been identified as risk factors for type 1 diabetes, a disease that involves autoreactive T cells targeting pancreatic beta cells." (PMID 41283441, 2025). "This shape-based nature enabled us to discover multiple unique protein–phenotype links, including cathepsin H and type 1 diabetes (rs2289702 within CTSH), TREM-like transcript 2 protein and monocyte count (rs62396355 within TREML2) or plexin-B2 and systolic blood pressure (rs28379706 within PLXNB2)." (PMID 34819519, 2021). "Other type 1 diabetes-associated regions that contribute are the INS, IL21 and CTSH gene regions." (PMID 31438962, 2019). "The score for the CTSH gene region, in which SNP genotypes were previously reported to be associated with clinical remission at 1 year from diagnosis in children with type 1 diabetes, was strongly associated with age at onset but not with C-peptide persistence." (PMID 31438962, 2019).
prostate carcinoma (11 papers, 2011 to 2026). A carcinoma that arises from epithelial cells of the prostate gland. "Cathepsin H (CtsH)-mediated processing of Talin1 has been observed in metastatic PC-3 prostate cancer cell lines, where increased CtsH expression is co-localized with Talin1 in focal adhesions." (PMID 41584041, 2026). "Dysregulated expression of CTSH has been reported in various cancers, including breast cancer, prostate cancer, and glioma." (PMID 40977731, 2025). "E2 possibly reduced the metastatic potential of prostate cancer through reduced expression of proteins such as cathepsin H (CTSH), extracellular matrix remodeling, and β-catenin." (PMID 39598420, 2024). "CTSH mediates talin processing and promotes prostate cancer migration by regulating integrin activation and adhesion strength." (PMID 39048806, 2024). "In prostate cancer CTSH has been shown to increase metastases via modulations of integrin activation." (PMID 37064098, 2023). "In human prostate cancer cells, inhibition or knockdown of CTSH increases αvβ3 integrin activity and their adhesion strength." (PMID 36589798, 2022). "Increased expression of CTSH, in particular, has been found in the malignant progression of prostate cancer." (PMID 32101552, 2020). "In a study of cathepsin H localization in a prostate cancer cell line, the cathepsin co-localizes with talin, a leading-edge protein associated with focal adhesions in cell migration." (PMID 31736973, 2019). "Silencing of cathepsin H in prostate cancer cells reduced migration and promoted activation of ανβ3 integrin, thus confirming the biological relevance of cathepsin H interaction with talin." (PMID 31555270, 2019). "Using Western blot we have detected different processing forms of CTSH in human prostate cancer (PC-3), osteosarcoma (HOS) and pro-monocytic (U937) cell lines." (PMID 22933963, 2011). "In order to clarify whether cathepsin H also regulates BMP-4 in humans, its impact on BMP-4 expression, processing and degradation was investigated in prostate cancer (PC-3), osteosarcoma (HOS) and pro-monocytic (U937) human cell lines." (PMID 22933963, 2011).
narcolepsy (8 papers, 2013 to 2024). A sleep disorder characterized by a tendency for excessive sleepiness during the day which occurs even after adequate sleep in the nighttime. "We discovered an association between the CTSH cis-pQTL (rs34593439) and narcolepsy, a condition for which immune-mediated dysregulation has been considered as one of the potential causes." (PMID 38521921, 2024). "Indeed, the main predisposing HLA gene for narcolepsy, DQB1*0602, also acts as a protective factor for T1D, whereas CTSH mutations are an odd factor for both T1D and narcolepsy." (PMID 36358399, 2022). "In addition to a strong signal in the T cell receptor alpha (TRA@), variants in two additional narcolepsy loci, Cathepsin H (CTSH) and Tumor necrosis factor (ligand) superfamily member 4 (TNFSF4, also called OX40L), attained genome-wide significance." (PMID 23459209, 2013). "Our study of nearly 2000 narcolepsy cases compared to 10,000 controls underscored important roles for HLA DQB1*06:02 and the T cell receptor alpha genes and implicated two additional genes, Cathepsin H and TNFSF4/OX40L, in disease pathogenesis." (PMID 23459209, 2013).
lung carcinoma (7 papers, 2022 to 2025). "After removing SNPs with p > 1e‐5 and F < 10, we conducted two‐sample MR analyses to explore the potential associations between CTSH and lung cancer and its subtypes." (PMID 41473685, 2025). "Our research, which integrated MR analysis from multiple sources, found a modest association between CTSH and lung cancer risk." (PMID 41473685, 2025). "To enhance the credibility of our findings, we performed a meta‐analysis of the IVW results from three datasets, which revealed an OR = 1.06 (95% CI = 1.03–1.09, P < 0.01), further confirming that high CTSH levels increased lung cancer risk." (PMID 41473685, 2025). "The co‐localization analysis revealed that overall lung cancer, lung adenocarcinoma, and CTSH shared a common causal variant at chromosome 15 rs34593439 with a PPH4 value of 0.99 (PPH4 > 0.8), indicating high support for shared causal variants." (PMID 41473685, 2025). "CTSH is linked to lung cancer, particularly adenocarcinoma, with modest effects mediated by metabolites like omega‐3 fatty acids." (PMID 41473685, 2025). "Based on the previous findings, it was evident that there was a significant association between CTSH and lung cancer, particularly with lung adenocarcinoma." (PMID 41473685, 2025). "In conclusion, the primary genetic evidence from this study reveals that high levels of cathepsin H increase the risk of lung cancer, particularly adenocarcinoma and lung cancer among smokers." (PMID 37805623, 2023). "The analyses conducted in this study demonstrated that cathepsin H increased the risk of overall lung cancer, adenocarcinoma, and lung cancer among smokers." (PMID 37805623, 2023). "A multivariable analysis using nine cathepsins as covariates reveals that elevated cathepsin H levels lead to an increased overall risk of lung cancer, adenocarcinoma, and lung cancer in smokers." (PMID 37805623, 2023). "The findings of the univariable MR analysis revealed that high levels of cathepsin H increased the risk of overall lung cancer (Inverse-Variance Weighted (IVW): p = 3.357 × 10–5, OR = 1.060, 95% confidence interval (CI) = 1.035–1.102)." (PMID 37805623, 2023). "Univariable MR analysis results revealed that elevated cathepsin H levels significantly increased the risk of lung cancer among ever smokers (p = 2.429 × 10–6, OR = 1.095, 95% CI = 1.055–1.138)." (PMID 37805623, 2023). "The conclusions provided herein clarify the partial association between cathepsin H and lung cancer reported in previous observational research and clinical studies." (PMID 37805623, 2023). "A Mendelian randomization analysis identifies a potential causal link between cathepsin H and lung cancer risk." (PMID 37805623, 2023). "The univariable Mendelian randomization analysis results indicate that elevated cathepsin H levels increase the overall risk of lung cancer, adenocarcinoma, and lung cancer among smokers." (PMID 37805623, 2023). "These discrepancies suggest that while CTSH may be linked to lung cancer, the effect is small, and further studies with larger sample sizes are needed to confirm these associations." (PMID 41473685, 2025). "Ultimately, our study suggests that elevated CTSH levels may be associated with an increased risk of overall lung cancer and lung adenocarcinoma, consistent with the significantly elevated serum CTSH levels observed in histological lung tumor patients." (PMID 41473685, 2025). "Although a previous Mendelian randomization (MR) study had preliminarily established a causal link between lung cancer and CTSH, single database‐derived results might be coincidental due to sample population differences." (PMID 41473685, 2025). "Therefore, except for overall lung cancer, adenocarcinoma, and lung cancer among smokers, the current evidence is insufficient to establish any causal link between cathepsin H and squamous cell carcinomas or SCLC." (PMID 37805623, 2023).
lung carcinoma (continued). "This may introduce notable biases into the relationship between cathepsin H and the risk of lung cancer." (PMID 37805623, 2023). "Subsequently, Bayesian colocalization analysis was performed to putatively identify whether cathepsin H drove the risk of lung cancer among ever-smokers by sharing pathway effects with smoking." (PMID 37805623, 2023). "Subsequently, given the potential variations in the pathogenesis of distinct lung cancer subtypes, we conducted an in‐depth investigation to elucidate the specific metabolic characteristics that mediate the relationship between CTSH and overall lung cancer." (PMID 41473685, 2025). "Subsequently, we further analyzed the mediating role of 233 metabolic traits between CTSH and lung adenocarcinoma and overall lung cancer." (PMID 41473685, 2025). "To address the limitations of previous studies, we integrated multiple databases to validate the relationship between CTSH and lung cancer, and also conducted an in‐depth analysis of the mediating effects of 233 metabolic traits." (PMID 41473685, 2025). "Future research should urgently delve into the mechanisms by which CTSH and lipid metabolic traits collectively influence lung cancer development." (PMID 41473685, 2025). "We then used a two‐step method to explore the mediating effects of 233 metabolic traits, deepening our understanding of CTSH's role in lung cancer." (PMID 41473685, 2025). "Lung cancer is a major global malignancy with debated roles for cathepsin H (CTSH), a lysosomal protease, and underexplored regulation by metabolites." (PMID 41473685, 2025). "This study explores the link between CTSH and lung cancer, covering global trends in lung cancer and hyperglycemia, MR analysis of CTSH and 233 metabolic traits, and scRNA analysis, along with multi‐level validation of CTSH expression in LUAD." (PMID 41473685, 2025). "Although previous MR studies suggested a potential relationship between CTSH and lung cancer, their reliance on a single data source resulted in significant sample bias." (PMID 41473685, 2025). "CTSH elevated lung cancer and adenocarcinoma risks, with docosahexaenoic acid (22:6) and omega‐3 fatty acids driving adenocarcinoma progression." (PMID 41473685, 2025). "We further investigated the relationship between CTSH and lung cancer using CTSH protease GWAS data from the INTERNAL study." (PMID 41473685, 2025). "This study innovatively integrated multiple analytical methods, including regression model analysis, MR, and scRNA‐seq, to provide multi‐faceted evidence for understanding the relationship between CTSH and lung cancer." (PMID 41473685, 2025). "To clarify CTSH's role in lung cancer, we performed single‐cell transcriptome analysis to explore CTSH gene expression in different cell types within lung cancer tissues and conducted pathway enrichment analysis to validate the MR results." (PMID 41473685, 2025). "CTSH levels increased the risk of lung cancer (OR = 1.070, 95% CI = 1.027–1.114, P = 0.001, PFDR = 0.009), and CTSH levels decreased the risk of basal cell carcinoma (OR = 0.947, 95% CI = 0.919–0.975, P = 0.0002, PFDR = 0.002)." (PMID 38883596, 2024). "Next, we focused on the relationship between CTSH and specific lung cancer subtypes." (PMID 41473685, 2025). "CTSH progression in lung cancer may regulate the sPLA2-PKCδ-MAPKs-cPLA2α pathway by modulating SP-B maturation, thereby regulating lipid metabolism in the lungs." (PMID 38883596, 2024). "The findings indicated that cathepsin H has a causal effect on the risk of lung cancer, rather than serving as a mediator in the pathway from smoking to lung cancer." (PMID 37805623, 2023). "Therefore, the mechanism of cathepsin H in relation to lung cancer becomes more complex, and further research is needed to elucidate the role of cathepsin H in lung cancer." (PMID 37805623, 2023). "In conclusion, cathepsin H may serve as a marker for lung cancer, potentially inspiring directions in lung cancer diagnosis and treatment." (PMID 37805623, 2023).
lung carcinoma (continued). "Additionally, reverse MR analysis of GWAS data for CTSH and lung cancer subtypes revealed no reverse causality." (PMID 41473685, 2025). "Thus, broader research is required to elucidate CTSH's role in lung cancer." (PMID 41473685, 2025). "Thus, it was essential to investigate the potential connection between CTSH and lung cancer." (PMID 41473685, 2025). "Therefore, our findings highlight a potential pathway in which metabolic stress may upregulate CTSH, thereby contributing to lung cancer progression." (PMID 41473685, 2025). "Consequently, we concluded that a high level of cathepsin H was a hazardous risk factor for developing lung cancer, rather than a mediator of the causal relationship between smoking and lung cancer." (PMID 37805623, 2023). "Furthermore, reverse MR analysis was performed, the results of which showed no reverse causality between cathepsin H levels and lung cancer risk among individuals with a history of smoking." (PMID 37805623, 2023). "Cathepsin H (CTSH), as a member of the cysteine protease family, had also attracted attention for its potential role in the pathogenesis of lung cancer." (PMID 41473685, 2025). "It has been reported that CTSH plays a metastasis-promoting role in hepatocellular carcinoma, whereas its role in lung cancer is not clear." (PMID 39839650, 2024). "In addition, our study had not yet explored the function of CTSH in lung cancer at the macrophage level, indicating that further experimental studies were required to confirm these findings." (PMID 41473685, 2025).